CD2AP (CD2 associated protein)
Diseases named in the same sentence as CD2AP in open-access papers (continued):
Sharing a sentence is not in itself a finding about the gene and the disease.
kidney disease (16 papers, 2012 to 2025). "A possible unifying model is that perturbations of the vascular system caused by CD2AP alterations are a common denominator underlying renal diseases and AD." (PMID 40462155, 2025). "In described cases of renal disease due to CD2AP variants, the age of onset is generally quite young (ages 2–21), and it is possible that with prolonged follow-up these individuals may eventually develop pathology consistent with AD." (PMID 40462155, 2025). "In addition, low levels of CD2-associated protein (CD2AP) mRNA in urinary exosomes were associated with an increased risk of kidney disease." (PMID 37189669, 2023). "Given its role in podocyte function, genetic variations and environmental stressors affecting CD2AP expression contribute to proteinuric kidney diseases, particularly FSGS." (PMID 41368354, 2025). "As a novel noninvasive tool, urinary exosome mRNA expression of CD2AP enables the assessment of renal function and fibrosis in patients with kidney disease." (PMID 37020588, 2023). "Renal disease-associated genetic variants have been found in key components of the SD such as Nephrin (NPHS1) and Podocin (NPHS2), as well as CD2AP." (PMID 35265622, 2022). "Finally, the article draws important parallels between kidney and brain physiology based on vascular and molecular organization, links kidney disease to AD, and suggests the existence of a kidney-brain axis in AD centered on CD2AP." (PMID 40462155, 2025). "Finally, we draw fundamental parallels between CD2AP-dependent mechanisms in AD and kidney disease, and propose a kidney-brain axis centered upon vascular CD2AP in AD." (PMID 40462155, 2025). "Mutations in proteins that are specific for podocyte development and function, including α-actinin-4, nephrin, podocin, CD2AP, and TRPC6, lead to renal disease that is caused by the rearrangement of the actin cytoskeleton and the disruption of the filtration barrier." (PMID 31118506, 2019). "Intervening on CD2AP may be the pathophysiological basis developing the proteinuria in renal disease." (PMID 22675377, 2012). "However, the role of CD2AP in tuning of TCR signaling in T cell immune responses or the impact of altered TCR signaling quality in vivo caused by Cd2ap deficiency has not been defined due to a fatal kidney disease that develops around 3 weeks of age in Cd2ap−/− mice." (PMID 29734372, 2018). "However, this may not be a suitable approach to treat kidney diseases associated with reduced expression or lack of CD2AP." (PMID 28878342, 2017).
infection (8 papers, 2016 to 2026). The state of being infected such as from the introduction of a foreign agent such as serum, vaccine, antigenic substance or organism. "In fact, the long-term infection was also associated with low expression of Cd2ap which has been previously associated with AD pathology aggravated by increased deposition of Aβ and Tau-induced neurotoxicity." (PMID 35177758, 2022). "This suggests, for example, targeting interaction with SH3 domain proteins such as BIN1 and CD2AP, which play redundant roles in the infection of different alphaviruses." (PMID 39556619, 2024). "Comparable numbers of LCMV-gp-specific CD4 T cells also were detected in both genotypes eight days after infection, suggesting that CD2AP is dispensable for priming and initial expansion of LCMV-specific CD4 T cells." (PMID 29734372, 2018). "Following reconstitution of donor-derived hematopoiesis, the recipient mice were infected with LCMV-c13 and contribution of Cd2ap-deficient and -sufficient cells to the TFH compartment was examined 22 days after infection." (PMID 29734372, 2018). "The successful infection decreased the expression of synaptopodin, CD2AP and nephrin and increased that of Snail." (PMID 27571062, 2016). "Both Cd2ap−/− and control LCMV-specific CD4 T cells differentiated into Ly6C+ TH1 effector cells or TFH cells as defined by CXCR5 and PD-1 expression on day 8 after infection." (PMID 29734372, 2018). "We could detect no convincing accumulation of CD2AP in the early stages of infection, suggesting that CD2AP is unlikely to play a role in invasion." (PMID 29520916, 2018).
neurodegenerative disease (3 papers, 2022 to 2025). A disorder of the central nervous system characterized by gradual and progressive loss of neural tissue and neurologic function. "Twenty-seven of these associations are known disease loci reported in GWAS, including APOE, MME, CD2AP, CD33 and IL34 for AD, and CD40, CD58, EVI5, IL7R and STAT3 for MS, and 23 associations represent previously unreported genetic associations with neurodegenerative diseases." (PMID 40037332, 2025).
immune disorder (1 paper, 2017). "As regards to the non-syndromic forms, some are related to a still not completely understood underlying immune disorder, while an increasing number is found to be caused by mutations in genes highly expressed in podocytes (e.g. NPHS1, NPHS2, CD2AP, PLCE1, ACTN4, TRPC6, and INF2)." (PMID 28298181, 2017).
neurological disease (1 paper, 2023). "Some genes, such as CD2AP, FCER1G, MAPK3, and EPHX2, were in nodes or core nodes of this neurological disease network, indicating that the CpG sites and these target genes may influence AD development." (PMID 38092781, 2023).
CD2AP also shares sentences with these, for which no sentence is quoted: glomerulopathies (3 papers); vascular dementia (3); acute promyelocytic leukemia (1); allergic rhinitis (1); autoimmune disease (1); cervical cancer (1); colon adenocarcinoma (1); COVID-19 (1); epilepsy (1); Fabry disease (1); fibrosis (1); Glomerular sclerosis (1); hay fever (1); head and neck squamous cell carcinoma (1); hepatocellular carcinoma (1); IgA nephropathy (1); kidney (1); lung adenocarcinoma (1); lung squamous cell carcinoma (1); Pick disease (1); progressive supranuclear palsy (1); prostate carcinoma (1); Proteinuria (1); rheumatoid arthritis (1); schizophrenia (1); Senile plaques (1); systemic lupus erythematosus (1); type 2 diabetes (1).